SMN1 (survival of motor neuron 1, telomeric)
Diseases named in the same sentence as SMN1 in open-access papers (continued):
Sharing a sentence is not in itself a finding about the gene and the disease.
spinal muscular atrophy (continued). "Another MND disease is spinal muscular atrophy (SMA), an inherited condition with an autosomal-recessive pattern affecting lower motor neurons that degenerate due to a lack of survival motor neuron (SMN) protein encoded by the SMN1 gene." (PMID 34441299, 2021). "Both cases presented the similar phenotype of predominant lower motor neuron signs with rather symmetrical involvement of proximal muscles at onset in upper and lower limbs, a pattern very similar to spinal muscular atrophy (SMA), ruled out by the absence of SMN1 mutations in both cases." (PMID 32948071, 2020). "Notably, genetic evaluation excluded a differential diagnosis of alternate conditions, including spinal muscular atrophy (SMA), through negative SMN1/SMN2 deletion/duplication analysis, and Pelizaeus-Merzbacher disease, as PLP1 mutation analysis was negative." (PMID 40243727, 2025). "However, a higher-order multiplexing dPCR assay for measuring SMN1 and SMN2 copy numbers in spinal muscular atrophy (SMA) samples has not been reported." (PMID 33199817, 2020).
motor neuron disease (27 papers, 2009 to 2025). "Spinal muscular atrophy is a severe motor neuron disease caused by inactivating mutations in the SMN1 gene leading to reduced levels of full-length functional SMN protein." (PMID 20019802, 2009). "It is a motor neuron disease resulting from a mutation in the SMN1 gene." (PMID 41008984, 2025). "SMA is a common motor neuron disease that results from loss-of-function mutations in the SMN1 gene." (PMID 41053315, 2025). "If the patient has two copies of SMN1, consideration should be given to other motor neuron disorders." (PMID 38673907, 2024). "In the case of motor neuron diseases (MND) such as ALS or SMA, loss of the survival motor neuron 1 (SMN1) gene results in severe motor activity deficiency and muscle atrophy, largely due to a massive loss of motor neurons." (PMID 22662195, 2012). "While mutations in the SMN1 gene on chromosome 5q13 are the most common cause of inherited motor neuron disease in children, a small subset of patients (around 4%) do not exhibit SMN1 mutations or deletions." (PMID 39457470, 2024). "With respect to other motor neuron diseases, it is presently unclear whether increasing SMN1 or SMN2 expression would be beneficial or detrimental." (PMID 27014701, 2016). "As a consequence, reduced levels of full-length SMN protein produced from the SMN2 gene, while sufficient to prevent embryonic lethality, are not able to fully compensate for the loss of SMN1 resulting in motor neuron disease." (PMID 23967270, 2013). "To test if IGF-2 could also protect against degeneration across motor neuron diseases, we used motor neurons derived from SMA patient iPSCs, which degenerate due to a lack of SMN1 protein." (PMID 27180807, 2016).
spinal muscular atrophy, type 1 (15 papers, 2012 to 2025). A severe infantile form of proximal spinal muscular atrophy characterized by severe and progressive muscle weakness and hypotonia resulting from the degeneration and loss of the lower motor neurons in the spinal cord and the brain stem nuclei. "Spinal muscular atrophy type 1 (SMA1) is an autosomal recessive neuromuscular disease mainly caused by a homozygous mutation or deletion in the SMN1 gene." (PMID 37213895, 2023). "We hereby report the identification of a novel splice site variant in compound heterozygosity with the SMN1 exon 7 and 8 deletion in a 3-month-old girl presenting with SMA type I symptoms." (PMID 37799281, 2023). "The variant has been found in compound heterozygosity with SMN1 exons 7/8 deletion, thus causing an SMA type 1 phenotype in a female patient." (PMID 37799281, 2023). "We note that the causative gene for Werdnig-Hoffman disease is survival motor neuron 1 (SMN1) and that for Krabbe disease is galactocerebrosidase (GALC)." (PMID 36447271, 2022). "In 2019, an adeno-associated virus (AAV)-9-based gene therapy was approved for the treatment of infantile spinal muscular atrophy (SMA)-1 with a 1-time intravenous (IV) administration of the self-complementary (sc)-AAV9 encoding the survival motor neuron type 1 (SMN1) gene." (PMID 31998120, 2019). "The neuronal apoptosis inhibitor protein (NAIP), found on chromosome 5 in close proximity to SMN1, is mutated in greater than half of all SMA type 1 cases and loss of SMN1 itself may also lead to motor neuron cell death through apoptosis." (PMID 22723941, 2012). "This gene-replacement strategy has been clinically successful, leading to the first licensed virally mediated gene replacement for a severe neurological disease, spinal muscular atrophy type 1 (SMA1), which is caused by loss of SMN1 in spinal motoneurons." (PMID 39895633, 2025). "Onasemnogene abeparvovec (Zolgensma, formerly AVXS-101), a gene replacement therapy comprising an AAV vector containing the survival motor neuron 1 (SMN1) gene, has also been developed for spinal muscular atrophy type I." (PMID 35163674, 2022). "The loci for the diseases for which GLBs have been reported are as follows: Werdnig-Hoffman disease, survival motor neuron 1 (SMN1) on 5q13.2; Krabbe disease, galactocerebrosidase (GALC) on 14q31.3; and 13q deletion syndrome, [46, XY, del (q22q31)]." (PMID 36447271, 2022). "Based on these symptoms Motorplex panel (analysis of genes causing muscle disorders) was performed resulting in a homozygous deletion for SMN1, compatible with diagnosis of type 1 SMA." (PMID 32234058, 2020). "For example, the intravenous infusion of an adeno-associated viral (AAV) vector containing full-length copies of survival motor neuron 1 (SMN1) has shown success in treating spinal muscular atrophy type 1 (SMA1), a disease characterized by motor neuron degeneration." (PMID 37307819, 2024). "AAV9 vector efficiency at penetrating the BBB has proven to be sufficient for the delivery of the SMN1 gene to lower motor neurons in spinal muscular atrophy type 1, leading to the FDA approval of the AAV9-SMN1 vector, Zolgensma." (PMID 38256124, 2024).
amyotrophic lateral sclerosis (11 papers, 2013 to 2026). Amyotrophic lateral sclerosis (ALS) is a neurodegenerative disease characterized by progressive muscular paralysis reflecting degeneration of motor neurons in the primary motor cortex, corticospinal tracts, brainstem and spinal cord. "These disorders include, among others, Parkinson's disease (PD) with SNCA, PINK1, PARK2, GBA1, and LRRK2 mutations, amyotrophic lateral sclerosis (ALS) with TDP43 mutation, Huntington's disease (HD) with HTT mutation, and Spinal muscular atrophy (SMA) with SMN1 mutation." (PMID 27313629, 2016).
muscular atrophy (7 papers, 2012 to 2024). The loss of muscle tissue due to inactivity or disease. "It is caused by mutations/deletions of the survival motor neuron 1 (SMN1) gene and is typified by the loss of spinal cord motor neurons, muscular atrophy, and in severe cases, death." (PMID 22397316, 2012). "The sco paralysis phenotype could be tied to loss of gas1a, a factor involved in skeletal myogenesis, and/or smn1, which is associated with skeletal muscle atrophy, caused by progressive loss of motor neurons." (PMID 35079792, 2022). "Spinal Muscular Atrophy Type 1 (SMA1, OMIM # 25330) results from the loss of cell-autonomous SMN1 and subsequent motor neuron loss." (PMID 29776328, 2018). "SMA is characterized by MN degeneration, due to deletion or mutation of the telomeric SMN1 gene and to the insufficient efficiency of SMN2 gene: this determines in the affected patients muscular atrophy, paralysis and reduced lifespan, according to the disease severity." (PMID 29440993, 2018).
muscle atrophy (4 papers, 2018 to 2025). "Spinal Muscular Atrophy (SMA) is a neurodegenerative disorder affecting lower motor neurons (MNs) and leading to muscle atrophy, due to mutation of the SMN1 gene, which encodes SMN protein." (PMID 41402453, 2025). "It is caused by deletion or intragenic pathogenic variants of the causative gene SMN1, which degenerates anterior horn motor neurons and leads to progressive myasthenia and muscle atrophy." (PMID 39343938, 2024). "The disease is caused by the deletion/mutation of the survival motor neuron 1 (SMN1) gene resulting in progressive skeletal muscle atrophy and paralysis, due to the degeneration of spinal motor neurons (MNs)." (PMID 30233310, 2018).
Prader-Willi syndrome (4 papers, 2018 to 2023). "Genetic tests for Prader-Willy syndrome, SMN1, and DM1 resulted negative." (PMID 34262519, 2021).
respiratory failure (3 papers, 2020 to 2026). The significant impairment of gas exchange within the lungs resulting in hypoxia, hypercarbia, or both, to the extent that organ tissue perfusion is severely compromised. "It is caused by the mutation or deletion of the survival motor neuron 1 (SMN1) gene resulting in lower motor neuron (MN) degeneration followed by motor impairment, progressive skeletal muscle paralysis and respiratory failure." (PMID 38561840, 2024). "For instance, SMA, where patients are characterized by progressive degeneration of spinal motor neurons, muscle atrophy, symmetric limb paralysis, and respiratory failure, is caused by mutated SMN1 gene." (PMID 32764415, 2020). "We report the case of a 19-year-old female patient with genetically confirmed SMA type III (zero copies of SMN1, two copies of SMN2) whose disease course was complicated by chronic respiratory failure with hypercapnia requiring non-invasive ventilation and intractable generalized epilepsy." (PMID 42299170, 2026).
Batten disease (2 papers, 2012 to 2015). "This application is similar to the multiple-exon-skipping detection assay (MESDA) used to study SMN1 and SMN2 isoform expression in different Batten disease cell lines." (PMID 25866926, 2015).
cystic fibrosis (2 papers, 2015 to 2022). Autosomal recessive disorder caused by pathogenic variants in the CFTR gene (cystic fibrosis transmembrane conductance regulator), which encodes a chloride and bicarbonate channel expressed in epithelial cells, and follow the diagnosis criteria. "Thirty-four males and 63 females performedkaryotype and screening for the more common pathogenic variants forCFTR-related cystic fibrosis and spinal muscularatrophy (SMN1) in the Portuguese population." (PMID 35916466, 2022).
myasthenia (2 papers, 2020 to 2024). "The clinical manifestations of SMAX2 are similar to the typical SMA symptoms caused by SMN1 variants, such as hypotonia, tendon areflexia, and severe myasthenia." (PMID 32181232, 2020).
myotonic dystrophies (2 papers, 2023 to 2024). "NGS also has some technical limitations, making it particularly challenging to detect repeat expansions (myotonic dystrophies) or variants in genes with highly homologous pseudogenes (e.g., SMN1 and SMN2)." (PMID 38127101, 2024). "Interestingly, a similar sharp cut-off between alternative and constitutive splicing has been reported in myotonic dystrophy (DM1/DM2) with similar genes being affected, namely CELFs, MBNLs, NOVA, SMN1/2 and SF3A1, among others." (PMID 36282542, 2023).
) protein deficiency (1 paper, 2021). "The disorder is caused by survival motor neuron (SMN) protein deficiency, resulting from loss of function mutation or deletion of the SMN1 gene, but retention of the companion SMN2." (PMID 34445199, 2021).
acute lymphoblastic leukemia (1 paper, 2021). Leukemia with an acute onset, characterized by the presence of lymphoblasts in the bone marrow and the peripheral blood. "For instance, increasing the expression of SMN2 may have clinical utility in patients with spinal muscle atrophy owing to SMN1 mutations, and increased expression of PAX2 or PAX8 may be of interest in patients with predisposition to acute lymphoblastic leukemia due to PAX5 mutations." (PMID 34818036, 2021).
Arthritis (1 paper, 2023). Inflammation of a joint. "Thus, the limited expression of SMN1 induced by PCB may contribute to keeping the levels of these proinflammatory cytokines during arthritis under control, as a previously observed effect of PCB on these cytokines in a model of experimental autoimmune encephalomyelitis." (PMID 37936684, 2023).
Cerebellar atrophy (1 paper, 2021). Cerebellar atrophy is defined as a cerebellum with initially normal structures, in a posterior fossa with normal size, which displays enlarged fissures (interfolial spaces) in comparison to the foliae secondary to loss of tissue. "We think it would be worth considering testing for GEMIN5 variants in SMN1 negative neonates with severe hypotonia and absent reflexes, especially with cerebellar atrophy on imaging." (PMID 33963192, 2021).
cognitive deficits (1 paper, 2021). "One may hypothesize that cognitive deficits could have developed due to a deficiency in the SMN1 protein in the CNS, and patients with SMA type 2 and a more severe disease course would have a lower probability of attaining a university entrance qualification." (PMID 34573206, 2021).
cystinosis (1 paper, 2024). Cystinosis is a metabolic disease characterized by an accumulation of cystine inside the lysosomes, causing damage in different organs and tissues, particularly in the kidneys and eyes. "Therefore, one of the color channels previously used for cystinosis detection was used for TREC detection, while SMN1 detection remained the same." (PMID 39596667, 2024).
dystrophinopathy (1 paper, 2021). "CNVs such as exon deletion in SMN1 in SMA, exon deletion or duplication in dystrophinopathy, PMP22 duplication in Charcot–Marie–Tooth diseases could be evaluated by MLPA, specific GPS or WGS." (PMID 33919863, 2021).
hepatocellular carcinoma (1 paper, 2023). A malignant tumor that arises from hepatocytes. "Furthermore, their inhibitory effects on Hep-G2 cell proliferation suggest that their corresponding target proteins, CYC1 and SMN1, may be critical for the survival of hepatocellular carcinoma cells." (PMID 37594310, 2023).
hereditary spastic paraplegia (1 paper, 2015). Hereditary spastic paraplegias (HSP) comprise a genetically and clinically heterogeneous group of neurodegenerative disorders characterized by progressive spasticity and hyperreflexia of the lower limbs. "The PMP22 duplication is the most common cause of CMT; spinal muscle atrophy is mostly caused by deletions in the SMN1 gene and deletions of SPAST have been identified in hereditary spastic paraplegia." (PMID 25648254, 2015).
laryngeal squamous cell carcinoma (1 paper, 2024). A squamous cell carcinoma that arises from the larynx. "A recent report showed a multi-fold increase in expression of SMN1/SMN2 transcripts in laryngeal squamous cell carcinoma (LSCC)." (PMID 38214229, 2024).
male infertility (1 paper, 2024). The inability of the male to effect fertilization of an ovum after a specified period of unprotected intercourse. "We hope our report serves as a catalyst to invite more investigations into the role of SMN1/2 circRNAs in processes associated with SMA and other pathological conditions, including cancer and male infertility." (PMID 38714739, 2024).
nail-patella syndrome (1 paper, 2024). A rare hereditary patellar dysostosis characterized by nail hypoplasia or aplasia, aplastic or hypoplastic patellae, elbow dysplasia, and the presence of iliac horns as well as renal and ocular anomalies. "Distinct genetic disorders were also identified, including nail patella syndrome, Meckel–Gruber syndrome, and deletions in smn1." (PMID 38775502, 2024).
neuroblastoma (1 paper, 2021). Neuroblastoma (NB) is the most common solid, extracranial childhood tumor. "To evaluate whether SMA-miRs could modify SMN1 or SMN2 expression levels, we performed transient transfections of SH-SY5Y neuroblastoma cells with commercial mimics or scramble." (PMID 34542403, 2021).
osteoporosis (1 paper, 2025). A condition of reduced bone mass, with decreased cortical thickness and a decrease in the number and size of the trabeculae of cancellous bone (but normal chemical composition), resulting in increased fracture incidence. "Moreover, the increased trabecular bone pattern factor (Tb.Pf) in Smn1-cKD group indicated a transition in trabecular morphology from plate-like to rod-like structures, suggesting a phenotype of osteoporosis." (PMID 41320719, 2025).
prostate carcinoma (1 paper, 2024). A carcinoma that arises from epithelial cells of the prostate gland. "Since CBs underwent clear alterations upon platinum drug treatment in prostate cancer cells as measured via Coilin and SMN1 localization, we quantified this phenomenon using Coilin as a marker." (PMID 38218884, 2024). "Since CBs underwent drastic changes upon platinum drug exposure as measured by translocation of two significant CB proteins Coilin and SMN1, we then asked what other proteins might be involved in CB homeostasis in prostate cancer cells." (PMID 38218884, 2024).
scoliosis (1 paper, 2025). A congenital or acquired spinal deformity characterized by lateral curvature of the spine. "Among Chinese publications, the most frequently used keywords were SMA, SMN1, ALS, SMN2, nusinersen, prenatal diagnosis, survival motor neuron, gene therapy, scoliosis, and alternative splicing." (PMID 40153758, 2025).
sporadic amyotrophic lateral sclerosis (1 paper, 2024). Sporadic amyotrophic lateral sclerosis is a amyotrophic lateral sclerosis in which there is no known cause, such as no family history. "For example, duplications of the SMN1 gene, supposedly resulting in higher levels of SMN, are associated with sporadic amyotrophic lateral sclerosis." (PMID 39456991, 2024).
neuromuscular disease (39 papers, 2011 to 2025). "Loss-of-function mutation of the survival of motor neuron 1 (SMN1) gene, which results in insufficient levels of SMN protein, is the causes of the neuromuscular disease, SMA." (PMID 41053315, 2025). "Spinal muscular atrophy (SMA) is an autosomal recessive, progressive neuromuscular disease characterized by a deficiency in the survival of motor neuron (SMN) protein, caused by loss-of-function mutations of or deletions within the SMN1 gene." (PMID 38943396, 2024). "The advent of SMN1‐enhancing approaches has brought unprecedented advances to the world of neuromuscular diseases and the combination of disease‐modifying therapies with presymptomatic diagnosis has completely revolutionised the face of SMA." (PMID 38600653, 2024). "SMA is a neuromuscular disease characterized by the degeneration of spinal motor neurons and caused by reduced levels of the RBP SMN due to deletions or, less frequently, mutations in the SMN1 gene." (PMID 32961072, 2020). "Between April 2017 and December 2020, infants with genetically confirmed SMN1 deletions and two SMN2 copies, with no signs and symptoms of neuromuscular disease, were enrolled and received treatment by six weeks of age." (PMID 40868194, 2025).
genetic disease (21 papers, 2014 to 2026). "For example, SMN1 gene whose mutations are responsible for the genetic disorder SMA and its homolog SMN2 gene are extremely similar." (PMID 32555294, 2020). "Thus, our novel nucleic acid diagnostics combining CRISPR/Cas14a1 and asymmetric PCR not only provides specific and sensitive testing of the deletion of SMN1 exon 7, but also holds promise for an accurate detection platform of genetic diseases and pathogens in multiple sample types." (PMID 35624569, 2022).